IL18 (interleukin 18)
Diseases named in the same sentence as IL18 in open-access papers (continued):
Sharing a sentence is not in itself a finding about the gene and the disease.
infection (continued). "In contrast to our findings here demonstrating IL‐1β exacerbates IAV disease, studies in gene‐deficient mice have shown that IL‐18 plays a protective role during HKx31 and PR8 infection by limiting viral replication, mediating interferon‐γ production as well as NK and T‐cell responses." (PMID 33834544, 2021). "However, excessive production of IL-18 by epithelial cells after infection with high dose of T. gondii contributes to intestinal pathology by inducing IFNγ." (PMID 34938670, 2021). "Furthermore, we showed that the infection stimulated the release of inflammatory cytokines IL-1β and IL-18, induce inflammation, and eventually promoted pyroptosis of macrophages." (PMID 33678162, 2021). "It is unclear whether neutrophils are directly producing this cytokine in our model of infection and whether IL-18 production is dependent on inflammasome activation." (PMID 34047696, 2021). "However, as the infection progressed, sustained levels of type I interferon signaling in neutrophils led to excess amounts of IL-18." (PMID 34047696, 2021). "IL-18 can induce cell-mediated immunity following infection with microbial product such as LPS." (PMID 33803000, 2021). "Additionally, APCs secrete IL-12, IL-15, and IL-18, which stimulate IFNγ secretion at the infection site." (PMID 34938670, 2021). "Consequently, the levels of IL-18 in mice serum gradually increased 6 and 24 h after infection with A. baumannii, P. aeruginosa, and E. coli." (PMID 34073235, 2021). "Infection by genetically diverse clinical strains of M. tuberculosis revealed an upregulation of NFKB1 and NFKB2 transcriptional factors that lead to the transcription of IL1β, while IL18 was slightly down-regulated at 48 h infection by East-Asian and Euro-American lineages." (PMID 34502407, 2021). "We speculate that upon infection of hMDM with T3SS/flagellin-deficient S. Typhimurium, IL-1β and IL-18 are processed in a caspase-8–dependent manner and released in a GSDMD-independent way." (PMID 33380493, 2021). "A study of acute Aspergillus infection determined 72 h after infection IL-18 mediates protection independently of IFN-γ, suggesting that the IL-18/IFN-γ axis occurs rapidly and IL-18 continues to mediate immunity independently of IFN-γ if the infection persists." (PMID 33643264, 2021). "Moreover, IL-1β and IL-18 as pro-inflammatory cytokines prevent the infection of pathogens effectively, yet excess pro-inflammatory cytokines is harmful to the host." (PMID 34777393, 2021). "The production of proinflammatory cytokines CXCL10 and IL-6 increased in both HRV16 and HRV1B infection (p < 0.05 for each), whereas IL-8 and IL-18 production increased in HRV1B infection (p = 0.025 and p = 0.018, respectively), but not in HRV16 infection (p = 0.314 and p = 0.674, respectively)." (PMID 34838080, 2021). "Regarding the inflammatory cytokine contents in mice after infection, the contents of TNFα, IFNγ, IL-1β, and IL-18 in serum, spleen, and ileum of mice challenged with ΔhtpG strains were significantly decreased (p < 0.05) as compared with mice challenged with WT strains." (PMID 34869065, 2021). "The analysis of variance between IL-1β, IL-18, IL-6, IL-8 and caspase-1 levels, showed statistically significant differences related to the infection conditions or the time after infection (6, 18 and 24 h.p.i.)as well as the interaction between these two factors." (PMID 34947890, 2021). "Thus, a new paradigm emerges that during mucosal pathogen infection, infiltrating Ly6Chi monocyte produces IL-12p70 or IL-18 that instructs NK cells or T cells to produce IFNγ." (PMID 34512626, 2021). "After 12 h, the relative expression of TNFα, iNOS, IL-1β, and IL-18 in the ΔhtpG infection group was significantly lower than that in the WT infection group (p < 0.01), and the relative expression of IL-1β and IL-18 was extremely lower than that in the CΔhtpG infection group (p < 0.01)." (PMID 34869065, 2021).
infection (continued). "In contrast, IL-18 only slightly induces IFNγ after low dose of infection." (PMID 34938670, 2021). "In that study, the levels of serum IL-18 were also found to be increased in parallel with those of serum IL-10 in Lm-infected B6 mice at 72 h post-infection, whereas B6.Nlrp3−/− mice had significantly reduced serum IL-18, which indicated that NLRP3 expression is relevant for IL-18 production." (PMID 35053151, 2021). "Infection with NTS serovars is known to stimulate an enhanced Th1-type bias by CD4+ or CD8+ T cells associated with increased production of proinflammatory cytokines IFN-γ, IL-18, IL-12, IL-15, and TNF-α." (PMID 33956909, 2021). "Intrigued by our finding of a sharp delineation of pathogen-induced mitochondrial cell death and cytokine release in our ex vivo infection model, we assessed whether IL-1β and IL-18 levels correlate with severity of disease in TB patients." (PMID 34718331, 2021). "Pyroptosis of neutrophils and monocytes is a major source of IL-18 during infection." (PMID 34257519, 2021). "Although IL-18-targeted biologic therapy may be effective in AOSD patients, the economic burden and potential risk of severe infection should be considered." (PMID 34344968, 2021). "However, IL-18 is produced by porcine DC-enriched PBMC following live tachyzoite infection, which, as we demonstrated, plays an important role in IFNγ induction by NK cells." (PMID 34576723, 2021). "An in vitro study proved that the Z. morio hemolymph can reduce the expression of pro-inflammatory factors, including interleukin-1β (IL-1β) and interleukin-18 (IL-18), which suggests that Z. morio hemolymph can be used as a novel therapeutic drug to reduce pathogen infection in animals." (PMID 34941846, 2021). "In addition, being part of the human host defense against infection, elevated IL-18 was reported to correlate with infection severity and outcome." (PMID 32998441, 2020). "Following the infection of the periodontal pathogen, namely P. gingivalis, it was found that the release of IL-1β, IL-6, and IL-18; the gene expression of pro-IL-1β and pro-IL-18; and the activity of caspase-1 in wild-type mice were significantly enhanced in comparison to NLRP3-deficient mice." (PMID 33271934, 2020). "For that purpose, we verified whether BMDMs deficient in components of the pathway were able to release IL-1β, IL-1α, and IL-18 in the same manner as WT cells in response to the infection by live tachyzoites." (PMID 32523898, 2020). "The loss-of-function rs479333 variant did not affect IL-1ß in our in-vitro model of infection, but was associated with a lower level of IL-18 both in vitro and in vivo (TB patients' plasma)." (PMID 33193317, 2020). "Furthermore, mRNA levels of factors activated by the NLRP3 inflammasome (IL-1β and IL-18) were significantly decreased in Gm28309 overexpressed cells, but higher in S2308 infection group, as well as protein secretion levels detected using ELISA." (PMID 33414782, 2020). "Furthermore, during infection with Y. enterocolitica, β1‐integrin signalling triggered by the adhesin invasin increases pro‐IL‐18 levels in IECs; notably, these outcomes are counteracted by YopH and YopE (Thinwa, Segovia, Bose, & Dube, 2014)." (PMID 32185892, 2020). "Inflammasomes are protein scaffolds required for the activation of caspase-1 and the subsequent release of interleukin (IL)-1β, IL-18, and danger signals, as well as the induction of pyroptotic cell death to restore homeostasis following infection and sterile tissue damage." (PMID 32962268, 2020). "Role of the inflammasome-related cytokines Il-1 and Il-18 during infection with murine coronavirus." (PMID 32256705, 2020). "Consistent with this, ΔospC3 infection caused cleavage of GSDMD and maturation of IL‐18, which are hallmarks of pyroptosis, whereas ΔospD3 infection did not (Fig EV1B)." (PMID 32657447, 2020). "Inflammasome activation and IL-1beta and IL-18 processing during infection." (PMID 32638896, 2020).
infection (continued). "Notably, co-administration of IL-12 and IL-18 in the first week after infection in BALB/c mice strongly activated Th1 cells and protective immunity suggesting a synergistic mechanism for induction of Th1." (PMID 33415318, 2020). "As previously reported, THP-1 cells produced IL-18 after infection with HSV-1." (PMID 32101570, 2020). "And then the downstream pathway is activated, thereby promoting the expression of NF-κB and the secretion of inflammatory cytokines, such as IL-1β and IL-18, which play a key role in recruiting neutrophils to sites of infection and promote inflammatory anti-bacterial immune responses." (PMID 32823867, 2020). "Moreover, UV-irradiated HSV-1 led to more IL-18 production at 24 hours post-infection, suggesting more robust inflammasome signaling in response to UV-irradiated HSV-1 in both IFNγ stimulated and unstimulated macrophages." (PMID 32101570, 2020). "Thus, epithelial cells dynamically respond to dietary vitamin A to regulate interleukin 18 production and potentiate resistance to infection." (PMID 32330185, 2020). "However, we found that UV-irradiating the virus led to an increase in IL-18 in ΔAIM2 THP-1 cells at 24 hours post infection, suggesting that the virus has evolved other mechanisms to inhibit inflammasome activation in macrophages that are not AIM2 dependent." (PMID 32101570, 2020). "We analyzed the effect of IL-18 reconstitution in stopΔIEC mice on day 3 of infection." (PMID 32330185, 2020). "Interestingly, UV-irradiating HSV-1 prior to infection also led to a robust increase in IL-18 release in the ΔAIM2 THP-1 cell line compared to WT virus." (PMID 32101570, 2020). "IL-18 reconstitution in stopΔIEC mice restored resistance to Salmonella by promoting epithelial cell shedding to eliminate infected cells and limit pathogen invasion early in infection." (PMID 32330185, 2020). "However, infection in the presence of cathelicidin promotes caspase-1 activation, release of IL-1β and IL-18, and the influx of neutrophils." (PMID 30978238, 2019). "Thus, it is likely that the protective role of NLRP6 during the initial phase of infection in VVC is stimulated by the vaginal microbiome with the production of IL-18." (PMID 31681274, 2019). "Infection with T. cruzi also induces the production of IL-12 and IL-18." (PMID 30717382, 2019). "Although all viruses increased the levels of IL-18 in hTCEpi cells compared to mock-infected hTCEpi cells, the virulent HSV-1 strains (17, McKrae, and KOS79) induced significantly higher levels of IL-18 early at 2 h post-infection compared to less-virulent HSV-1 strains (F, RE, KOS, and KOS63)." (PMID 31367214, 2019). "Interestingly, IL-18 was found at even higher levels in skin blister fluid from DENV patients collected during the acute phase of the infection as compared to plasma." (PMID 31467285, 2019). "Thus, the increased levels of the proinflammatory cytokines suggested that vvIBDV infection boosted the mRNA level of major inflammatory cytokines IL-1β and IL-18." (PMID 31632367, 2019). "To further understand the histological inflammatory response in the bursa, we assessed whether proinflammatory cytokines IL-1β and IL-18 were triggered during vvIBDV infection." (PMID 31632367, 2019). "Moreover, TLR11-/- mice sustained these elevated levels of IL-18 compared to TLR11xCasp1/11-/- mice by day 8 post-infection." (PMID 31194844, 2019). "In addition, in the case of patients with HIV-1, a remarkable increase in IL-18 expression was reported during the viral replication phase and progression of the infection." (PMID 31554368, 2019). "Although the activation of NLRP3 inflammasome is largely beneficial to the host defense during infections and metabolic processes, over production of IL-1β and IL-18 results in sterile inflammation, which can increase the risk of developing metabolic and autoinflammatory diseases among patients." (PMID 30873162, 2019).
infection (continued). "The peak of IL-18 production in the initial phase of infection was not affected in mice deficient of IL-22." (PMID 31681274, 2019). "Overall, these data suggest that IL-18 treatment might be an alternative and useful treatment for infection by extracellular pathogens, even in immunocompromised individuals." (PMID 30717382, 2019). "Additionally, the vvIBDV infection triggered MIF in vivo earlier than the upregulation of IL-1β/IL-18 transcription." (PMID 31632367, 2019). "The NLRP3 inflammasome is a multiprotein platform that is activated upon cellular infection or stress and subsequently leads to caspase-1-dependent secretion of proinflammatory cytokines, such as IL-1β and IL-18, and an inflammatory form of cell death termed as pyroptosis." (PMID 31222000, 2019). "Interestingly, Nlrc4−/− mice phenocopied Il22−/− mice as IL-18 levels were unaffected in the early phase of the infection but dramatically reduced in the later phase, consistent with previous findings showing that IL-22 and NLRC4 works along the same pathway." (PMID 31681274, 2019). "Pyroptosis was beginning to be noticed in Salmonella and Shigella species infection, starting with the formation of the inflammasomes and leading to the maturation and release of IL-1β and IL-18 and subsequent inflammatory cascade reaction, and was exclusively dependent on caspase-1." (PMID 31814872, 2019). "Immunoblots confirmed the presence of active caspase-1 p20 and proteolytic processing of pro-IL-18 upon infection with wild-type (WT) EPEC but not the T3SS-deficient ΔescF mutant." (PMID 31018119, 2019). "Endogenous IL-18 is also involved in defense against infection by Yersinia enterocolitica." (PMID 30717382, 2019). "Only RFX1 and IL18 genes showed significant downregulation after 48 h infection." (PMID 29867904, 2018). "In the present study, we found an early increase in urinary IL-18 separate from other factors that might increase it systemically, such as infection." (PMID 30399190, 2018). "Taken together, these findings suggest that IL-1β, IL-18, and caspase-1 may have different physiological function in the host response during infection." (PMID 29616195, 2018). "Interleukin-18, a linked IL-1 pro-inflammatory cytokine, signals in a complex with IL-18 receptors α (Rα) and β (Rβ) chains and induces IFN-γ that is essential for defense against infections." (PMID 29686666, 2018). "Inflammasomes, which are activated by cell infection and stress, have the potential to trigger the activation of caspase-1, which cleaves the pro-IL-1β and IL-18 into their mature forms, resulting in IL-1β and IL-18 secretion." (PMID 29773990, 2018). "Interestingly, IL-18 was downregulated under conditions of LASV infection relative to those of mock or MOPV infection." (PMID 30419076, 2018). "IL-18 is a potent inducer of IFNγ, a cytokine required to survive infection with B. thailandensis." (PMID 29791511, 2018). "Whereas the relevance of blocking IL-18 during infection has been investigated, the specific contribution of the vIL-18BP GAG-binding properties to poxvirus pathogenesis remains unknown." (PMID 29946427, 2018). "Because IL-1β and IL-18 are upregulated by caspase-1, caspase-1 may mediate additional mechanisms such as pyroptosis, which supports the importance of its regulation during infection." (PMID 29616195, 2018). "Therefore, it seems that the induction of diverse NKT cell effector functions by CD169+ macrophages and IL-18 is a conserved mechanism observed upon infection with various pathogens and in autoimmune disorders." (PMID 29249358, 2018). "In addition, these data also highlight how the nature of the pathogen and route of infection can dictate dependence of Th1 lineage cells on IL-1 or IL-18 signals." (PMID 30093707, 2018). "Also, most of IL18 expression in uninfected mice was restricted to splenic MΦs while after infection splenic MOs expressed high levels of the IL18 gene." (PMID 29408905, 2018).
infection (continued). "We found that IL-1β and IL-18 mRNA, as well as protein levels of mature IL-1β (p17) and cleaved fragment of pro-caspase-1 (p10) were significantly increased at 18 h post infection (p.i.), suggesting that inflammasome signaling was activated at early stage of YM infection." (PMID 30470758, 2018). "This furin cleavage feature could be transferred to other poxviruses to analyze in infection models the impact that blocking IL-18 at different sites will have on pathogenesis." (PMID 29946427, 2018). "Thus, IL-18 processing when studied early after infection can serve as a marker for inflammasome priming, defined as signaling events independent of new protein synthesis." (PMID 29632532, 2018). "However, in our case, genotype VIII NDV AF2240 induced higher expressions of the tested proinflammatory cytokines (CXCLi2, IFN-γ and IL-18) but with lower viral load in the chicken bursa than in the case of NDV IBS002 infection." (PMID 28569155, 2017). "A higher level of IL-18 is related to infection mortality (p = 0.001)." (PMID 28474577, 2017). "In our study, the plasma levels of IL-18, IL-6, and IL-1ß were associated with infection-cause mortality but not CV-cause mortality." (PMID 28474577, 2017). "Prominent among inflammatory pathways in monocytes/macrophages are caspase-1-activating platforms called “inflammasomes” that control maturation and secretion of interleukins such as IL-1β and IL-18, whose potent pro-inflammatory activities direct host response to infection and injury." (PMID 28489580, 2017). "IL-18 is a key mediator in the host response to infection and the inflammatory response." (PMID 29371912, 2017). "Both IL-18 and CXCLi2 gene expressions were also up-regulated during the infection of AF2240." (PMID 28569155, 2017). "To test whether this finding extends to tissue resident DCs, we monitored secretion of IL-1β and of IL-18 (which is undetectable in BMDCs) by splenic DCs after infection with flagellin-expressing STm." (PMID 29253868, 2017). "Furthermore, immunomodulatory effects of AMP-B became manifest upon exposure to cytokines such as IL-2 and IL-18, a situation that likely occurs during the course of infection and transformation." (PMID 28608807, 2017). "Notably, infection with X4550(pYA3334-SspH2-EscI) induced significantly more IL-1β and IL-18 secretion from peritoneal macrophages than that induced by X4550(pYA3334-SspH2) or X4550(pYA3334) (P < 0.05)." (PMID 28468643, 2017). "Moreover, OMV treatment of BMM led to the release of large amounts of IL-1β and IL-18 in an MOI-dependent manner whereas infection with P. gingivalis only led to minimal amounts of these mediators being produced." (PMID 28824884, 2017). "Age- and sex-matched wild-type C57BL/6 mice were infected subcutaneously with 104 CFUs of F. novicida wild-type or strains deficient for the putative effectors, and the bacterial burden in the liver and spleen as well as serum IL-18 levels were assessed at 2 days post infection." (PMID 28621333, 2017). "Therefore, monocytes with activated inflammasomes can produce inflammatory cytokines (IL-1 and IL-18) in the tissue, far from the original site of infection." (PMID 29167459, 2017). "ECTV-infection significantly (P > 0.01) inhibited TLR4 agonist + ATP-induced IL-18 production." (PMID 29312229, 2017). "In addition, the authors showed that IL-18 was an important factor for immunity to C. parvum in Rag2−/− γc−/− mice and IL-18 promoted production of IFNγ by macrophages during infection." (PMID 28800747, 2017). "The inflammatory nature of the infection means that C. rodentium interactions with IECs take place in an environment rich in cytokines (e.g., interleukin-18 [IL-18], IL-22, IL-6, IL-1β, tumor necrosis factor alpha [TNF-α], interferon-γ) and infiltrating immune cells." (PMID 28988824, 2017).